Y_RNA (Y RNA )
Gene: Miscellaneous RNA gene on chromosome 16 (58,083,068 to 58,083,168, reverse strand). Ensembl gene ENSG00000207173.
Homologues: Orthologues: chimpanzee Y_RNA (99% identical), macaque Y_RNA (95% identical). Paralogues in human: Y_RNA (88% identical), RNY3 (87% identical), Y_RNA (87% identical), Y_RNA (86% identical), Y_RNA (85% identical), RNY3P1 (84% identical), Y_RNA (84% identical), RNY3P14 (83% identical), Y_RNA (83% identical), RNY3P16 (82% identical), RNY3P9 (82% identical), Y_RNA (82% identical), and 94 more.